ACSBG2 (acyl-CoA synthetase bubblegum family member 2)
Description:
Catalyzes the conversion of fatty acids such as long chain and very long-chain fatty acids to their active form acyl-CoAs for both synthesis of cellular lipids, and degradation via beta-oxidation. Can activate diverse saturated, monosaturated and polyunsaturated fatty acids. Has increased ability to activate oleic and linoleic acid. May play a role in spermatogenesis.
Synonyms: BGR; PRTD-NY3; DKFZp434K1635; BRGL; PRTDNY3
Tractability: Antibody: UniProt places it where antibodies can reach, with medium confidence.
Gene: Protein-coding gene on chromosome 19 (6,135,247 to 6,193,094, forward strand). Ensembl gene ENSG00000130377.
Subcellular location: Cytoplasm; Membrane
Subcellular location (Human Protein Atlas): Cytosol
Pathways (Reactome):
Metabolism: Synthesis of very long-chain fatty acyl-CoAs
Gene Ontology:
Molecular function: arachidonate-CoA ligase activity; fatty acyl-CoA hydrolase activity; long-chain fatty acid-CoA ligase activity; very long-chain fatty acid-CoA ligase activity
Biological process: fatty acid metabolic process; long-chain fatty acid biosynthetic process; long-chain fatty-acyl-CoA biosynthetic process
Cellular component: cytoplasm; cytosol; mitochondrion; membrane
Genetic constraint (gnomAD): Loss-of-function variants: 58 observed, 72.92 expected, observed/expected ratio (o/e) 0.8, 90% interval 0.64 to 0.99. The upper end of that interval is the gene's LOEUF score, 0.99, which puts it in group 4 of 6, group 1 being the genes least tolerant of losing a copy. Missense variants: 697 observed, 802.36 expected, observed/expected ratio (o/e) 0.87, 90% interval 0.81 to 0.93. Synonymous variants: 298 observed, 293.19 expected, observed/expected ratio (o/e) 1.02, 90% interval 0.92 to 1.12.
Homologues: Orthologues: chimpanzee ACSBG2 (99% identical), macaque ACSBG2 (90% identical), pig ACSBG2 (74% identical), rabbit ACSBG2 (73% identical), dog ACSBG2 (73% identical), rat Acsbg2 (71% identical), mouse Acsbg2 (69% identical), zebrafish acsbg2 (58% identical), tropical clawed frog acsbg2 (57% identical), Drosophila melanogaster bgm (40% identical), Drosophila melanogaster hll (36% identical), Caenorhabditis elegans acs-18 (21% identical), and 21 more. Paralogues in human: ACSBG1 (48% identical), ACSL1 (25% identical), ACSL5 (24% identical), ACSL6 (23% identical), ACSL4 (22% identical), ACSL3 (21% identical), SLC27A1 (16% identical), SLC27A4 (16% identical), SLC27A2 (15% identical), SLC27A6 (15% identical), SLC27A5 (15% identical), SLC27A3 (15% identical).
Diseases named in the same sentence as ACSBG2 in open-access papers:
ACSBG2 is named in the same sentence as 7 diseases in open-access papers, as found by Europe PMC text mining. Sharing a sentence is not in itself a finding about the gene and the disease. The quoted sentences say what the papers report.
cancer (1 paper, 2019). A tumor composed of atypical neoplastic, often pleomorphic cells that invade other tissues. "Other lncRNAs were mainly correlated with either immune-associated pathways, with lnc-CGRRF1-3:1 as an example, or cancer-associated pathways, with lnc-ACSBG2-1:1 and lnc-ANKRD54-1:1 as examples." (PMID 31810243, 2019). "For downregulated lncRNAs, lnc-ACSBG2-1:1 and lnc-BOD1-1:7, -1:8, and -1:9 exhibit similar landscapes of pathway enrichment, where their low expression correlates with a high expression of genes in immune- and cancer-associated pathways, as represented by a negative enrichment score." (PMID 31810243, 2019).
infection (1 paper, 2023). The state of being infected such as from the introduction of a foreign agent such as serum, vaccine, antigenic substance or organism. "ACSL5 has a preference for C16 to C20 substrates, whereas other acyl-CoA synthetases induced by infection (SLC27A2 and ACSBG2) are more active for VLCFA (C20 to C24)." (PMID 37862421, 2023).
tumor (1 paper, 2019). "For half of the downregulated lncRNAs, namely lnc-ACSBG2-1:1 and lnc-BOD1-1:7, -1:8, and -1:9, high lncRNA expression levels correlated with primary therapy outcome success and lower tumor grade, which further suggest potential tumor-suppressing roles." (PMID 31810243, 2019). "Eight downregulated lncRNAs—lnc-ACSBG2-1:1; lnc-ANKRD54-1:1; lnc-BOD1-1:7, -1:8, and -1:9; and lnc-MUC22-1:1, -1:7, and -1:8—demonstrated correlation between lower patient survival rate with lower expression of lncRNA, indicating a potential tumor-suppressing role for these lncRNAs." (PMID 31810243, 2019).
ACSBG2 also shares sentences with these, for which no sentence is quoted: lipid metabolism disorder (1 paper); lymphoblastic leukemia (1); Mitchell syndrome (1); oligospermia (1).